IL18 (interleukin 18)
Diseases named in the same sentence as IL18 in open-access papers (continued):
Sharing a sentence is not in itself a finding about the gene and the disease.
pancreatic cancer (continued). "Further study on the mechanism of IL18 in PDAC showed that Pin1 promoted the proliferation and progression of pancreatic cancer cells by increasing the expression of IL-18 and continuously activating NF-kB cell pathway." (PMID 35464869, 2022). "Otherwise, the interaction between p65 and Pin1 enhanced NF-κB signaling and activated IL-18, while the increased IL-18 continues to amplify NF-κB signaling, improving the understanding of regulation for NF-κB in pancreatic cancer." (PMID 35651786, 2022). "We applied Cox and LASSO regression analysis to develop a neuroendocrine regulation- and metabolism-related prognostic risk score model with three genes (GSK3B, IL18 and VEGFA) for pancreatic cancer." (PMID 36743929, 2022). "The prognostic risk score model contained three genes: GSK3B, IL18 and VEGFA, all of which were highly expressed in pancreatic cancer tissue and were associated with poor prognosis." (PMID 36743929, 2022). "From a functional point of view, on the one hand, IL18 is supposed to promote progression and invasiveness of pancreatic cancer cells." (PMID 36131941, 2022). "IL-18 has been shown to be increased in pancreatic cancer and can contributed to immunosuppression via regulatory B cells." (PMID 35052825, 2022). "In a similar manner, the pharmacological inhibition of NF-κB strongly reduced the invasive and migrating properties of IL-18-over-expressing pancreatic cancer cells." (PMID 34572768, 2021). "In agreement with our findings, other data proved that IL‐18 regulates NF‐κB signalling to implement its tumorigenic capacity, which supports the Pin1/NF‐κB/IL‐18 feedback loop in pancreatic cancer cells." (PMID 32347623, 2020). "Pin1 promoted pancreatic cancer cell proliferation and motility by increasing IL‐18 expression, while Pin1 knockdown also inhibited the tumour‐promoting effect of IL‐18." (PMID 32347623, 2020). "CNV-positive cells expressed Krt20, a marker of pancreatic cancer cells, and Aim2, which activates caspase 1 to process Il1 and Il18 precursors and regulates inflammasome activation." (PMID 32908137, 2020). "For CEA.IL-18-CAR T cells, IL-18 was secreted at high levels in the presence of CEA-positive pancreatic cancer cells, but only minimal IL-18 was detected when T cells were exposed to CEA-negative pancreatic cancer cells." (PMID 30828333, 2019). "In the present study study, we found that pancreatic cancer cell-derived IL-18 increases Breg-induced immunosuppression." (PMID 29599908, 2018). "We previously showed that levels of the inflammatory cytokine IL-18 were increased in patients with pancreatic cancer." (PMID 29599908, 2018). "In a recent study, a combined use of IL-18 as immunotherapeutic agent alongside a targeted inhibition of the NF-κB pathway emerged as potentially effective against pancreatic cancer." (PMID 28536364, 2017). "In pancreatic cancer patients indeed increased levels of several cytokines such as IL-6, IL-18 and TNF-alpha can be found." (PMID 20961421, 2010). "Here, we investigated IL-18 activation in pancreatic cancer cells after 5-FU treatment under low-nutrient conditions that mimic key features of the tumor microenvironment, using a monoclonal antibody we generated that specifically recognizes cleaved, active IL-18." (PMID 41940532, 2026). "Given that NLRP3 inflammasome activation and IL-18 production are critical in pancreatic cancer progression and considering IL-18’s role as a CXCR1/2 ligand promoting tumorigenesis and angiogenesis, 8 represents a promising marine-derived therapeutic candidate." (PMID 40422787, 2025). "IL-18 could have a pro-tumoral activity in certain types of cancers, such as in pancreatic cancer and multiple myeloma, as discussed in this review, and the source and frequency of IL-18 release may contribute to its effect." (PMID 37298187, 2023).
pancreatic cancer (continued). "Additionally, PIN1-induced IL-18 expression promotes pancreatic cancer cell proliferation and motility, whereas PIN1 knockdown inhibits the tumor-promoting effect of IL-18." (PMID 35954317, 2022). "Finally, to evaluate the risk and prognosis in pancreatic cancer more conveniently using pyroptosis-related genes, we constructed a prognostic model consisting of seven PRGs, including CASP4, GSDMC, NLRP1, PLCG1, IL-18, CASP1 and NLRP2." (PMID 35712482, 2022). "The evidence presented in this study shows that NLRP3-regulated IL-18-induced eosinophilic inflammation may be involved in promoting the pathogenesis of pancreatic neoplasm via the indicated pathways and promotes characteristics similar to human cancer." (PMID 34183442, 2021). "In addition, recombination human IL‐18 (rhIL‐18) enhanced the proliferation and invasiveness of pancreatic cancer cells, whereas this tumour‐promoting effect were eliminated by Pin1 knockdown." (PMID 32347623, 2020). "Moreover, IL-1βcan enhance the invasive capacity of pancreatic cancer cells, while free IL-18 levels are increased in the blood of pancreatic cancer patients and are associated with poor survival." (PMID 32974137, 2020). "Thus, we found that Pin1 potentially activated NF‐κB signalling and correlated with IL‐18 expression in pancreatic cancer cells." (PMID 32347623, 2020). "Notably, the keywords included T-cell differentiation, T-cell development, DNA methylation, histone modification, TH2 cell activation, CCL17 production, IL-18 secretion, and pancreatic cancer, all of which participate in either immune regulation or cancer." (PMID 33664764, 2020). "Furthermore, IL-18 is found to be responsible for the immunosuppression and decreased Teff activity in pancreatic cancer via inducing Breg proliferation, which then leads upregulation of PD-1 receptor in B cells." (PMID 32823814, 2020). "Serum IL-18 is increased in patients with cancer, and high levels of serum IL-18 is correlated with poor clinical outcomes in some types of cancers including breast and pancreatic cancers." (PMID 31731729, 2019). "Finally, the combination of a natural IL-18 inhibitor (IL-18BP) and a PD-1/PD-L1 inhibitor suppressed tumor growth and metastasis in a murine pancreatic cancer model." (PMID 29599908, 2018). "Both Pin1 and IL‐18 could enhance the NFκB activity in pancreatic cancer cells." (PMID 32347623, 2020). "Thus, inflammasome inhibition may suppress the pancreatic cancer cell growth via downregulation of IL-1β and IL-18." (PMID 32974137, 2020). "It was reported that higher plasma IL18 levels were associated with shorter recurrence-free survival (RFS) and overall survival (OS) in patients with triple-negative breast cancer, and IL18 overexpression in tumors was associated with shorter OS in patients with pancreatic cancer." (PMID 30586414, 2018). "Our results show that IL-18 and PD-1/PD-L1 could be therapeutic targets in pancreatic cancer." (PMID 29599908, 2018). "IL-18 has been detected in TME of patients with esophageal squamous cell carcinoma, pancreatic cancer, breast cancer, lung cancer, renal cell carcinoma, multiple myeloma, hepatocellular carcinoma, and oral cavity cancer." (PMID 37033931, 2023). "According to this study, PRGs risk models were defined with the combination of immune and signaling pathways genes (CASP4, GSDMC, NLRP1, PLCG1, IL-18, CASP1, and NLRP2), among which CASP4, NLRP1, PLCG1, IL-18, and CASP1 are overexpressed in pancreatic cancers." (PMID 37893166, 2023). "An additional risk model PRG based on more immune-related genes (CASP4, GSDMC, IL-18, NLRP1, NLRP2, PLCG1, TIRAP, and TNF) was developed, which can be used to predict pancreatic cancer prognosis with an accuracy of medium to high." (PMID 37893166, 2023).
pancreatic cancer (continued). "These p40-expressing CAR T cells not only had a better safety profile but also displayed better efficacy against neuroblastoma and pancreatic cancer CDXs by promoting antigen-dependent proliferation and CAR T-cell persistence compared to IL-15 or IL-18." (PMID 36059449, 2022). "Evidence has suggested that IL‐18 promotes proliferation and metastasis of pancreatic cancer cell lines through the NF‐κB signalling pathway; however, when co‐administered with BAY11‐7082, an NF‐κB inhibitor, IL‐18 improved survival in a murine model of PDAC." (PMID 32347623, 2020). "In an immune-competent model of bulky CEA-positive pancreatic cancer, a single injection of CEA.IL-18-CAR T cells led to prolonged survival compared to mice treated with 2nd generation CEA-CAR." (PMID 30828333, 2019). "Inflammation can be tumorigenic through multiple molecular mechanisms, including elevated inducible nitric-oxide synthase (iNOS), cyclooxygenase-2 (COX-2), interleukin (IL)-1β, IL-18, and P2X7 receptor (P2X7R), to name a few, and is found particularly in pancreatitis and pancreatic tumors." (PMID 29228654, 2017). "Indeed, through IP assay, we found that IL-18 did not be O-GlcNAcylated in pancreatic cancer cells (data not shown)." (PMID 38575607, 2024). "The simultaneous inhibition of the IL-18 and PD-L1/PD-1 pathways using synthetic inhibitors leads to reduced PDAC growth and metastasis in orthotopic animal models, highlighting the in vivo significance of Breg–cancer cell crosstalk in the progression of pancreatic cancer." (PMID 39682280, 2024). "In our study, a 1.5–1.9-fold reduction of IL-18 Bpa was observed in all patients post-VT1021 treatment, suggesting that plasmatic IL-18 Bpa could be a potential pharmacodynamic biomarker for VT1021 in patients with GBM and pancreatic cancer." (PMID 38773224, 2024). "Combined inhibition of IL-18 and PD-L1/PD-1 pathways with synthetic inhibitors reduces PDAC growth and metastasis formation in orthotopic animal models, reinforcing the in vivo relevance of the crosstalk between Breg and cancer cells for the progression of pancreatic cancer." (PMID 35359944, 2022). "However, the direct roles of IL-18 and eosinophils have never been established in the development of pancreatic neoplasms." (PMID 34183442, 2021). "Aberrant IL-6 and IL-18 levels both create a tumor microenvironment that is favorable for the tumor cells by promoting survival and establishing an immunosuppressive environment, suggesting that NLRX1 may protect against pancreatic tumors through regulating inflammation and inflammatory cytokines." (PMID 37342194, 2023). "Our results show that P2X7R (~20-fold), its key inflammasome components: caspase-1 (15-fold), IL-1β (~45-fold), and in addition to (data not shown) IL-18 (~35-fold), IL-33 (~93 folds), TNF-α (~13-fold) and COX-2 (~41-fold) are increased in pancreatic tumors compared to normal pancreas." (PMID 29228654, 2017).
gastric cancer (47 papers, 2011 to 2025). A primary or metastatic malignant neoplasm involving the stomach. "The expression of IL18 was lower in tumor-associated macrophages cultured with metastatic gastric cancer cell lines." (PMID 30061915, 2018). "Similarly, NLRP3-associated IL-18 is found in high levels in plasma of lymphoma and multiple myeloma patients where IL-18 is a predictor of poor survival in multiple myeloma patients, esophageal carcinoma, renal cell carcinoma and gastric carcinoma." (PMID 37298187, 2023). "Studies have shown that IL18 is highly expressed in the serum of gastric cancer patients, and endogenous IL18 can promote the metastasis of gastric cancer by enhancing the expression of CD44 and VGEF and inhibiting the expression of CD70." (PMID 36707882, 2023). "IL-18 promotes the immune escape of gastric cancer cells by upregulating programmed cell death 1 (PD1) in NK cells, downregulating CD70 in tumor cells and inhibiting the CASP8-mediated apoptosis in gastric cancer cells." (PMID 37833958, 2023). "Serum IL-18 levels in patients with gastric cancer and skin cutaneous melanoma have been correlated with cell migration and malignancy." (PMID 38201482, 2023). "Epithelial gastric cells-derived IL-18 binds to IL-18R, that is overexpressed on the gastric cancer cell membrane, and inhibits Caspase-8-mediated apoptosis while promoting tumor proliferation." (PMID 37891577, 2023). "Inflammatory cytokines that support gastric cancer-related inflammation include IL-1, IL-6, IL-18, TNF-α, and TGF-β." (PMID 35892729, 2022). "MR effect estimates for associations of circulating IL-18 with the risk of AML and IL-17 with stomach cancer." (PMID 35865545, 2022). "In conclusion, our findings provide evidence to support potential causal associations of IL-18 with AML and IL-17 with stomach cancer." (PMID 35865545, 2022). "We found that genetically predicted higher levels of IL-18 were associated with an decreased risk of AML, and IL-17 was associated with the risk of stomach cancer." (PMID 35865545, 2022). "In gastric cancer, IL-18 induced the expression of the pro-angiogenic factor, vascular endothelial growth factor (VEGF), which finally promoted tumor growth and metastasis." (PMID 36276078, 2022). "GSDMD was also involved in inducing the release of inflammatory factors such as IL-1β and IL-18, which can promote the growth of gastric cancer cells and accelerate the formation of gastric tumors through immunosuppression." (PMID 34384029, 2021). "Collectively, the study suggests the existence of a novel ASC/IL-18/NF-κB signaling axis that augments tumor cell survival in gastric cancer." (PMID 32117971, 2020). "CCL5, CCL22, CCL21, CCL2, and CCL15 were correlated with effector memory CD4 T cell in T1/T2 stage gastric cancer, and the number of cells was associated with the expression of IL3, IL17F, IL18, IL22, and IL31." (PMID 33426088, 2020). "A pro-tumorigenic function for ASC, through its effector cytokine IL-18, was recently described in gastric cancer, where ASC was significantly upregulated in the tumor compared to normal gastric tissue." (PMID 32117971, 2020). "Consistent with cell migration and angiogenesis being key steps in tumor metastasis, suppression of IL-18 expression in gastric cancer cells resulted in a reduction in both primary tumor growth and metastasis in vivo." (PMID 31231372, 2019). "ASC was shown to restrain the apoptosis of gastric cancer (GC) cells through an IL-18-mediated inflammation-independent mechanism." (PMID 31492049, 2019). "In that study, gastric cancer cells were treated with rhVEGF and the concentration measured of interleukin‐18 (IL‐18), which is involved in enhanced cell migration." (PMID 29632805, 2018). "IL18 also enhanced the migratory ability of cancer cells including pancreatic, breast, and gastric cancers." (PMID 30586414, 2018).
gastric cancer (continued). "Because IL-18 stimulates vascular endothelial cells and promotes metastatic tumor cell invasion, studies had examined the mechanisms of IL-18 secretion from gastric cancer cell line." (PMID 24115947, 2013). "Vascular endothelial cell growth factor-D (VEGF-D) increased the expression as well as the secretion of IL-18 from the gastric cancer cell line." (PMID 24115947, 2013). "Both IL-6 and IL-18 are predictors of prognosis in gastric cancer patients." (PMID 35892729, 2022). "Moreover, IL-18 enhances angiogenesis and promotes tumor cell proliferation and migration in gastric cancer." (PMID 34211462, 2021). "Indeed, studies in gastric cancer showed that IL-18 induces the expression of the pro-angiogenic factor, vascular endothelial growth factor (VEGF)." (PMID 31231372, 2019). "However, other studies showed that IL‐18 was able to promote tumor development and progression by showing higher levels of serum IL‐18 in patients with gastric cancer 13 or oral cancer." (PMID 30524946, 2018). "Another study showed that serum levels of IL-33 were significantly higher in patients with gastric cancer than healthy people, suggesting that serum IL-33 levels may have a closer correlation with gastric cancer than IL-18 levels." (PMID 27014647, 2015). "A possible explanation is that IL-18 may have promoted gastric cancer cells migration and invasion via the regulation of CD70, CD44 and VEGF expression in immune cells, which deserves our further investigation." (PMID 24223129, 2013). "The level of IL-18 in serum may be an indicator for the diagnosis of gastric cancer." (PMID 35292015, 2022). "Thus, by selectively upregulating IL-18 but suppressing IL-1β, H. pylori LPS not only inhibits the immune inflammatory response but also promotes gastric cancer cells’ escape from immune surveillance, which facilitates gastric cancer initiation and progression." (PMID 33217986, 2020). "In addition, it has been reported that serum IL-18 level may be used as a marker for monitoring the clinical course of patients with some cancer types, including esophageal, breast and gastric cancer." (PMID 24066061, 2013). "BIRC5, CLDN1, DDX58, IL18, NPC2, NUSAP1, and PHC3 were found to have higher expression in gastric cancer tissues compared to normal tissues, and their expression was also elevated in various other cancer types." (PMID 40393971, 2025). "More recently, the IL-18/ILC2 axis has also emerged in cancer research, shaping the immune landscape within the tumor microenvironment in CRC, gastric cancer, and CML." (PMID 40247153, 2025). "Cisplatin is a first-line drug in the treatment of gastric cancer.Concomitantly, P2X7 expression and the derived cytokine IL-18 have been recognizedas gastric cancer biomarkers." (PMID 38716980, 2024). "In gastric cancer, VEGF-enhanced production of IL-18 results in increased migration of human gastric cancer SNU-601 cells, followed by activation of the ERK signaling pathway." (PMID 35954317, 2022). "Herein, we further showed that famotidine stimulation in gastric cancer cells of BGC823 and AGS significantly promoted cell pyroptosis by inducing NLRP3 activation, leading to caspase-1 activation, IL-1β and IL-18 release." (PMID 34686215, 2021). "IL‐18 levels were increased by rhVEGF‐165 via the generation of ROI and ERK1/2 phosphorylation, which promoted migration of gastric cancer cells." (PMID 32347623, 2020). "The negative correlation between Erdr1 and IL-18 was also confirmed in a human gastric cancer cell line." (PMID 27941650, 2016). "Our study found that M.hy induced IL-1β promoted migration and invasion of the gastric cancer cells, while M.hy induced IL-18 did not contribute to the migration and invasion of gastric cancer cells, which was different from other reports." (PMID 24223129, 2013). "Importantly, it is IL-1β but not IL-18 produced from macrophages challenged with M.hy promoted gastric cancer cell migration and invasion." (PMID 24223129, 2013).
gastric cancer (continued). "Further results showed that famotidine triggered cell pyroptosis in gastric cancer cells by activation of NLPR3 inflammasomes including ASC, Caspase-1 and NLRP, leading to enhanced IL-18, not IL-1β, mature and secretion." (PMID 34686215, 2021). "Although IL‐6 and interleukin 18 were detected as SASP proteins, their levels were not affected by PITX2‐mediated lysosomal exocytosis, suggesting the involvement of alternative mechanisms in regulating SASP in gastric cancer." (PMID 40995693, 2025).